NEUROD2 (neuronal differentiation 2)
Diseases named in the same sentence as NEUROD2 in open-access papers:
NEUROD2 is named in the same sentence as 43 diseases in open-access papers, as found by Europe PMC text mining. Sharing a sentence is not in itself a finding about the gene and the disease. The quoted sentences say what the papers report.
medulloblastoma (8 papers, 2010 to 2023). A malignant, invasive embryonal neoplasm arising from the cerebellum. "To investigate the role of macrophages in SHH medulloblastoma, we employed a variety of mouse models of NeuroD2:SmoA15 as well as pharmaceutical approaches." (PMID 31160587, 2019). "This mouse model of the human SHH medulloblastoma subtype expresses an activated form of Smoothened (SmoA1) specifically in GNPs, under control of the NeuroD2 promoter (ND2)." (PMID 29234490, 2017). "Many tumor cells are known to exhibit high levels of glycolysis, and NeuroD2-SmoA1 medulloblastomas are consistently highly proliferative." (PMID 22407012, 2012). "Here, using immunostaining and blotting techniques in mouse NeuroD2-SmoA1 medulloblastomas, we detected very robust levels of PPARγ in the tumors as opposed to the adjacent non-tumor cerebellar tissues." (PMID 22407012, 2012). "mRNA transcripts for Bdnf (Brain-derived neurotrophic factor), Neurl (Neuralized homolog), Id4 (Inhibitor of DNA binding 4), and Neurod2 (Neurogenic differentiation 2) were up-regulated 5, 3.7, 2.7, and 2.2-fold in SmoA1 +; Pten +/− medulloblastomas." (PMID 20520772, 2010). "The NeuroD2:SmoA1 medulloblastoma model was also used to show that blocking TGF-β signaling promoted memory T cell development thereby conferring antitumor immunity and in Atoh1-Cre;Ptch1fl/fl mice, tumor astrocyte-derived Shh induced the proliferation of medulloblastoma tumor cells." (PMID 33869004, 2021). "To investigate whether TAMs and their associated genes are similarly increased in the murine model of SHH medulloblastoma, we stained NeuroD2:SmoA1 tumours with the pan-macrophage marker IBA1." (PMID 31160587, 2019). "With this in mind, we assessed key transiently activated neural transcription factors (MATH1, NHLH1), and other temporally activated genes (NEUROD1, NHLH2, NFIB, LPPR4, DPYSL3, NEUROD2) expressed throughout granule neuron differentiation, in the medulloblastoma subgroups." (PMID 25412507, 2014). "In order to determine whether glycolysis is increased in NeuroD2-SmoA1 medulloblastomas, we carried out immunostaining and western blot analysis of medulloblastomas and adjacent, non-tumorous cerebellum." (PMID 22407012, 2012). "Indeed, olomoucine treatment resulted in a striking reduction of PPARγ levels in the NeuroD2-SmoA1 medulloblastomas." (PMID 22407012, 2012). "Overall, our results showed that similar to human medulloblastoma, TAMs are activated in the NeuroD2:SmoA1 murine SHH model, rendering the model suitable to determine the functional role of TAMs in medulloblastoma." (PMID 31160587, 2019). "The optimal irradiation dosage and age of mice (tumor volume) for tumor relapse are determined using Math1-Cre/Ptch1loxp/loxp mice in this study, which may not be applicable to other medulloblastoma mouse models such as NeuroD2-SmoA1 mice." (PMID 37074909, 2023). "We also carried out western blotting of medulloblastoma and adjacent non-tumor tissue from NeuroD2: Smo/A1 mice, and we observed higher levels of IGFBP2 in tumor tissue; its levels were very low by comparison in a mouse model for Myc-amplified non-SHH medulloblastoma." (PMID 37029430, 2023).
schizophrenia (6 papers, 2020 to 2025). A major psychotic disorder characterized by abnormalities in the perception or expression of reality. "Mutations in Neurod2 are associated with schizophrenia and schizoaffective disorder, and Neurod2 polymorphism in patients with schizophrenia is associated with decreased verbal memory and executive functions." (PMID 36430421, 2022). "Neurogenic differentiation factor 2 (NEUROD2) is one of the most important neurogenic transcription factors in the CNS, which mutation is associated with schizophrenia." (PMID 33424550, 2020).
breast carcinoma (5 papers, 2006 to 2025). "Additionally, NEUROD2 has been associated with breast cancer formation." (PMID 40585860, 2025). "Among the genes amplified in the focal regions were a cluster of HOX genes (HOXA7, HOXA9, HOXA10, HOXA11) on 7p15, AKT1 (14q32.33), IGF1R (15q26.3), ERBB2 and NEUROD2 (17q12), all of which have been reported in primary breast cancers." (PMID 24489661, 2014). "NEUROD2 itself, coding for a protein that plays a role in neuronal differentiation and neuronal cell fate, is unlikely to be involved in breast cancer prognosis." (PMID 25906114, 2015).
autism (4 papers, 2021 to 2024). Persistent deficits in social interaction and communication and interaction as well as a markedly restricted repertoire of activity and interest as well as repetitive patterns of behavior. "In mice, NEUROD2 knockout selectively increases excitability of layer V neurons, while in humans, haploinsufficiency of NEUROD2 is associated with intellectual disability, autism, and speech delay." (PMID 39693421, 2024). "Additionally, Neurod2 depletion induces dysregulated expression of ion channels, elevation of ExN action potentials in response to depolarizing current injections as well as the manifestation of autism-like behaviors." (PMID 37995133, 2023). "Recently56 reported that NEUROD2 knockout mice display synaptic and physiological defects in CPN along with autism-like behavior abnormalities (where NEUROD2 is a transcription factor involved in early neuronal differentiation)." (PMID 38233398, 2024).
Intellectual disability (4 papers, 2021 to 2024). "Through a collaborative effort, we gained access to 6 families with NEUROD2 heterozygous missense mutations associated with NDD including intellectual disability, ASD and speech delay." (PMID 34188164, 2021). "Our findings demonstrate crucial roles for Neurod2 in neocortical development, whose alterations can cause neurodevelopmental disorders including intellectual disability and ASD." (PMID 34188164, 2021). "The characteristic clinical features of NEUROD2-mutated patients include autistic traits, intellectual disability, and speech disturbance." (PMID 34188164, 2021). "Interestingly, the DECIPHER human genome database reports that a small, 135 kb-long duplication encompassing the whole NEUROD2 gene, is associated with intellectual disability and delayed language development." (PMID 34188164, 2021). "While a previous study has suggested that NEUROD2 is involved in early epileptic encephalopathy, our data point to a core NEUROD2-associated phenotype centered on ASD, intellectual disability, and speech disturbance." (PMID 34188164, 2021). "Informed by these neurobehavioral features in mouse mutants, we identified eleven patients from eight families with a neurodevelopmental disorder including intellectual disability and ASD associated with NEUROD2 pathogenic mutations." (PMID 34188164, 2021). "Informed by these neurobehavioral features in mouse mutants, we searched for and identified five families with pathogenic NEUROD2 mutations associated with intellectual disability, ASD, hyperactivity, and speech delay, with or without epilepsy." (PMID 34188164, 2021).
colon cancer (2 papers, 2011 to 2019). "The NEUROD2 gene was related to the metastasis and the survival for colon cancer." (PMID 31207989, 2019).
embryonal carcinoma (2 papers, 2017 to 2021). A non-seminomatous malignant germ cell tumor characterized by the presence of large germ cells with abundant cytoplasm resembling epithelial cells, geographic necrosis, high mitotic activity, and pseudoglandular and pseudopapillary structures formation. "It has been previously shown that the induction of the expression of NeuroD2 in Xenopus embryos and P19 embryonal carcinoma cell line, as well as in embryonic stem cells, is sufficient to induce neural differentiation." (PMID 28740463, 2017).
glioblastoma (2 papers, 2019 to 2020). The most malignant astrocytic tumor (WHO grade IV). "As miR-210 expression is associated with hypoxia, it’s targeting of NeuroD2 links undifferentiation status of cells in a hypoxic niche with the pathogenesis of glioblastoma." (PMID 30813461, 2019). "For example, miR‐210 strictly regulates the expression of NeuroD2, and overexpression of NeuroD2 reduces the invasiveness of glioblastoma under hypoxia conditions." (PMID 32125767, 2020). "Recently NeuroD2, the levels of which are tightly regulated by miR-210, was shown to act as a tumor suppressor and prognostic biomarker in glioblastoma." (PMID 30813461, 2019).
glioma (2 papers, 2011 to 2020). A benign or malignant brain and spinal cord tumor that arises from glial cells (astrocytes, oligodendrocytes, ependymal cells). "NeuroD2 is post‐transcriptionally targeted by miR‐210, overexpression of NeuroD2 diminishes glioma cell proliferation, migration, and promotes apoptosis under hypoxia." (PMID 32125767, 2020).
Stroke (2 papers, 2021 to 2022). Sudden impairment of blood flow to a part of the brain due to occlusion or rupture of an artery to the brain. "In glutamatergic neurons, we found neuron-associated TFs such as NEUROD2 to be significantly depleted in the stroke hemisphere, which corresponds with decreased neuronal cell types at punch position 8 in the stroke hemisphere." (PMID 33627658, 2021). "Using real-time RT-PCR of stroke brain tissues, we validated the expression of three selected neuronal genes from the network: Robo3, Lingo1, and NeuroD2, whose expression values were >2 in NPC-CM(M) than in NPC-CM(S)." (PMID 35887140, 2022).
Ataxia (1 paper, 2024). Ataxia refers to impaired coordination of voluntary muscle movement. "Knockout of NeuroD2 in a mouse model was previously shown to result in microcephaly, ataxia, and death at approximately 2 weeks." (PMID 38788202, 2024).
dyslexia (1 paper, 2024). A learning disorder characterized by an impairment in processing written words. "The dyslexia-disposing NEUROD2 variant (rs12453682) exhibited the second-strongest weight for this same impact mode (#10) (mode weight z score = 5.3)." (PMID 39693421, 2024).
epilepsy (1 paper, 2021). A brain disorder characterized by episodes of abnormally increased neuronal discharge resulting in transient episodes of sensory or motor neurological dysfunction, or psychic dysfunction. "While the transcription factor NEUROD2 has recently been associated with epilepsy, its precise role during nervous system development remains unclear." (PMID 34188164, 2021). "Indeed, two children with epilepsy and one child with neurodevelopmental delay were identified with rare de novo mutations in the DNA binding domain of NEUROD2, and functional testing in tadpoles suggested pathogenicity." (PMID 34188164, 2021). "Although a causative role for NEUROD2 in epilepsy is validated by the phenotypic overlap in two epileptic patients with similar mutations, a single patient with neurodevelopmental delay is currently insufficient to determine whether NEUROD2 is involved in NDDs." (PMID 34188164, 2021). "Indeed, Neurod2 mutation in the mouse recapitulates most features of the human phenotype: ASD-relevant social abnormalities and propensity to epilepsy and hyperactivity." (PMID 34188164, 2021). "In summary, Neurod2 HET and KO mice exhibited behavioral defects reminiscent of the symptoms seen in ASD (altered social interest and memory, stereotypies) and ASD comorbidities (epilepsy, hyperactivity)." (PMID 34188164, 2021). "Non-fully penetrant NEUROD2-associated phenotypes include ADHD symptoms (5/7 patients) and epilepsy (3/7 patients)." (PMID 34188164, 2021).
Epileptic spasm (1 paper, 2022). A sudden flexion, extension, or mixed extension-flexion of predominantly proximal and truncal muscles that is usually more sustained than a myoclonic movement but not as sustained as a tonic seizure. "We propose that epileptic spasms related to de novo NEUROD2 pathogenic variant respond well to combined vigabatrin and high-dose prednisolone therapy." (PMID 36494631, 2022). "However, there is limited information about the clinical and electroencephalographic response of epileptic spasm treatment in NEUROD2-related NDD syndrome." (PMID 36494631, 2022).
major depressive disorder (1 paper, 2019). An episode of depression lasting two or more weeks without an intervening episode of mania. "Increased Neurod2 expression levels were detected in the ventromedial prefrontal cortex of men with major depressive disorder compared to healthy control subjects." (PMID 30934833, 2019).
malignant glioma (1 paper, 2021). A grade III or grade IV glioma arising from the central nervous system. "Consistent with the glial nature of malignant gliomas, genes downregulated at T2 and End were enriched for neuronal differentiation and synaptic functions (e.g., DCX, NEUROD2, and SYN1)." (PMID 33390587, 2021).
microcephaly (1 paper, 2024). A congenital or acquired developmental disorder in which the circumference of the head is smaller than normal for the person's age and sex. "NeuroD2 was also found to be significantly decreased at both transcript and protein level in a model of Zika virus induced microcephaly." (PMID 38788202, 2024).
neuroblastoma (1 paper, 2011). Neuroblastoma (NB) is the most common solid, extracranial childhood tumor. "Transient expression of NeuroD2, one of neural basichelix-loop-helix, under the control of HSP activated by electrical stimulationconverted mouse neuroblastoma cells into differentiated neurons." (PMID 21533199, 2011).
rhabdoid tumor (1 paper, 2024). An aggressive malignant embryonal neoplasm usually occurring during childhood. "Interestingly, both NEUROG1 and NEUROD2 were hypermethylated and down-regulated in AT/RTs when compared to MBs in our DM-DE gene analysis and they harbor DMRs, which were hypermethylated in AT/RTs compared with PSCs and bound by BRD9 in rhabdoid tumors." (PMID 38499326, 2024).
tumor (13 papers, 2012 to 2025). "HER2 and NEUROD2 copy number gains were found to be associated with a high tumor grade, a high mitotic count and a decreased 5 year survival rate." (PMID 25906114, 2015). "In multivariate Cox regression analyses, NEUROD2 copy number gains exhibited an independent prognostic value next to tumor size." (PMID 25906114, 2015). "After multivariate Cox regression only tumor size and NEUROD2 gene copy number gain remained as independent prognostic factors." (PMID 25906114, 2015). "Although copy number gains of HER2 and NEUROD2 were associated with a high tumor grade, a high mitotic count and a decreased 5 year survival rate (p = 0.015), only tumor size and NEUROD2 copy number gains emerged as independent prognostic factors." (PMID 25906114, 2015). "Additionally, it is possible to use 3DISCO-LSFM to image established MB, as shown here in adult Neurod2-SmoA1+/− mouse where one can distinguish tumour and adjacent healthy tissue." (PMID 35680976, 2022). "Cell lines from multiple tumor types with 3, 4, 5 and 6 copies of NEUROD2 have very limited LOF effects, which could lead to incorrect correction of LOF effects in these cell lines if using approaches based on absolute copy number." (PMID 30722791, 2019). "Furthermore, our data showing dramatic acceleration of tumor formation upon deletion of Ndp from the Neurod2-SmoA1 MB model demonstrate that Norrin-dependent effects on tumorigenesis are independent of Ptch status in the endothelium." (PMID 27823583, 2016). "There are clear expression differences between clinicogeneticsubgroups, consistent both with the ANOVA analysis of CIS gene expression acrosssubgroups and with the presence of genespreviously shown to be highly expressed in Group 3 and 4 tumours (e.g.NEUROD2, GABBR2)." (PMID 24252690, 2013).
neurodegenerative disease (3 papers, 2017 to 2022). A disorder of the central nervous system characterized by gradual and progressive loss of neural tissue and neurologic function. "Combined with the expression levels in the brain and the supporting literature evidence related to neurodegenerative diseases in vivo and in vitro, we screened out FBXL20, PPP1R1B, NEUROD2 (NDF2), and ERBB2 (HER2) for follow-up molecular biology experiments." (PMID 35694256, 2022).
neurodevelopmental disorder (3 papers, 2021 to 2026). A behavioral and cognitive disorder with onset during the developmental period that involves impaired or aberrant development of intellectual, motor, or social functions. "Neuronal differentiation Factor 2 (NEUROD2) variants have recently been a cause of neurodevelopmental disorders (NDDs) and EIEEs with distinctive features." (PMID 36494631, 2022). "Recently, NEUROD2 mutation has been shown to be the causative of neurodevelopmental disorders (NDDs) with core clinical features including intellectual disability, autism spectrum disorders, and speech disturbance." (PMID 36494631, 2022). "Haploinsufficiency of NEUROD2 can cause neurodevelopmental disorders with or without seizures in human infants and causes spontaneous seizures in Xenopus tadpoles." (PMID 41815199, 2026).
cancer (2 papers, 2024 to 2025). A tumor composed of atypical neoplastic, often pleomorphic cells that invade other tissues. "To explore this idea, we reanalyzed six NEUROD2 and NEUROG2 induction experiments across diverse cell types, including embryonic stem cells (ESCs), P19 carcinoma cells and embryonic fibroblasts." (PMID 39494521, 2024).
infection (2 papers, 2017 to 2020). The state of being infected such as from the introduction of a foreign agent such as serum, vaccine, antigenic substance or organism. "The infection of PNCs with lentiviruses that express dCas9-KAT and a gRNA that recruits this chimeric protein to the most proximal KAT3 peak of Neurod2 prevented the downregulation of NeuroD2 observed in dKAT3-KO neurons." (PMID 32444594, 2020).
neurological diseases (2 papers, 2021 to 2022). "Neurod2 is positively associated with synapse formation, synaptic density protein level, and dendritic spine maturation, leading to the onset of neurological diseases." (PMID 36614117, 2022).
NEUROD2 also shares sentences with these, for which no sentence is quoted: Alzheimer disease (3 papers); autism spectrum disorder (2); adenocarcinoma (1); amyloidosis (1); amyotrophic lateral sclerosis (1); bipolar disorder (1); cognitive deficits (1); dementia (1); early infantile epileptic encephalopathy (1); Epileptic encephalopathy (1); Hyperglycemia (1); invasive ductal carcinomas (1); lung carcinoma (1); Neurodevelopmental delay (1); neuronal ceroid lipofuscinosis (1); primitive neuroectodermal tumor (1); Sandhoff disease (1); schizoaffective disorder (1).